LPL (lipoprotein lipase)
Diseases named in the same sentence as LPL in open-access papers (continued):
Sharing a sentence is not in itself a finding about the gene and the disease.
tumor (87 papers, 1991 to 2026). "A thorough examination of the LUAD dataset from TCGA showed that decreased LPL expression was associated with distinct molecular characteristics of LUAD tumor tissues." (PMID 40427755, 2025). "Recent studies have shown that LPL expression appears upregulated in several types of tumor cells and is associated with cancer progression and poor prognosis." (PMID 34834495, 2021). "LPL has previously been implicated in tumor progression, and results in zebrafish support the notion that lipid metabolism can regulate even the earliest stages of tumor progression." (PMID 32455885, 2020). "Decreased adipose tissue LPL activity was associated with hypertriglyceridemia during early stages of tumor growth in Lewis rats bearing a mammary adenocarcinoma." (PMID 25415607, 2014). "Reduction in AT LPL activity in tumor bearing mice to the levels of starved animals was associated with impaired lipid deposition, fat loss, reduced breakdown of plasma lipoproteins and increased circulating lipid concentrations." (PMID 25415607, 2014). "This association may be attributed to the involvement of LPL in lipid metabolism, thereby contributing to the maintenance of tumor microenvironment homeostasis and suppression of tumor growth and metastasis." (PMID 40107973, 2025). "Furthermore, we observed a significant upregulation of the gene encoding lipoprotein lipase Lpl (LPL) in isolated tumor-infiltrating leukocytes from the NI-1701 treated cohort, which we attributed to the dominant TAM subpopulation." (PMID 35538512, 2022). "Lipoprotein lipase (LPL; EC:3.1.1.34) is another lipid-related enzyme associated with tumor growth." (PMID 24932311, 2014). "Particularly noteworthy were the prominent positive correlations observed between LPL and B cells or neutrophils alongside macrophages or dendritic cell populations; these support the potential implications for LPL’s role in modulating tumor-associated immuno-microenvironments." (PMID 40427755, 2025). "Lipoprotein Lipase (LPL) is also linked to PCa by facilitating the uptake of fatty acids, which fuel tumor growth and proliferation." (PMID 41584049, 2026). "Lipoprotein lipase (LPL), an important enzyme that is responsible for the hydrolysis of triglycerides into fatty acids, presented elevated expression at the level of tumor tissue." (PMID 41041104, 2025). "While TTF1, CK7, and NAPSA are routinely utilized for tumor origin identification and classification, LPL offers a novel perspective by reflecting changes in tumor metabolism and the tumor microenvironment." (PMID 40427755, 2025). "In terms of TMB, LPL is positively correlated in 5 tumor types including GBM, LAML, THYM, OV, and ACC, while it is negatively correlated in 13 cancer types including GBMLGG, LGG, LUAD, COAD, and COADREAD." (PMID 40427755, 2025). "Due to the potential causal relationship between LPL and LUAD as well as its diagnostic value, herein, we further investigated the anti-tumor effect of enhancing the expression and activity of LPL." (PMID 40427755, 2025). "EC-derived ANGPTL4 promoted tumor angiogenesis by maintaining a glycolytic phenotype and inhibiting lipoprotein lipase (LPL)." (PMID 39567756, 2025). "FA metabolism is significantly enhanced in PTC; elevated expression of LPL, FATP2 and CPT1A was linked to tumor aggressiveness." (PMID 41041104, 2025). "One possible explanation is that, as suggested by immune cell infiltration analysis and single-cell transcriptomic data, LPL is predominantly expressed in the non-tumor components of the tumor microenvironment, particularly macrophages." (PMID 40427755, 2025). "Essentially, the study established a direct correlation between increased expression of the three enzymes and tumor aggressiveness: elevated levels of LPL, FATP2, and CPT1A were associated with lymph node metastasis and more advanced tumor stages." (PMID 41041104, 2025).
tumor (continued). "Our investigation showed that LPL gene expression was diminished in tumor cells, whereas it was significantly elevated in tumor-infiltrating myeloid cells." (PMID 40427755, 2025). "Hemizygous deletion of the LPL gene was observed in 45% of tumor samples, with promoter hypermethylation occurring in 45% of cases with the deletion and 22% without it." (PMID 40563400, 2025). "Regarding immune regulation, our study revealed a robust correlation between LPL expression and the presence of various immune cell populations within the tumor microenvironment." (PMID 40427755, 2025). "The expression level of LPL was also much higher in HCC tumor tissues than in paracancer tissues, as shown by IF and IHC." (PMID 38339301, 2024). "Similar to this, in HCC xenograft tumor models, sh-LPL also improved the inhibitory impact of TP on the tumor." (PMID 38339301, 2024). "In the context of HCC, lipoprotein lipase (LPL) has been demonstrated to boost tumor advancement by increasing the absorption of exogenous lipids." (PMID 38921460, 2024). "Circulating triglycerides must first be hydrolyzed by extracellular lipoprotein lipase (LPL) before being used by tumor cells." (PMID 38339301, 2024). "The results showed that LPL is still under-expressed in tumor cells and that SFRP2 is overexpressed in all HER2, Luminal A, and Luminal B subtype groups, and under-expressed in the Basal_like subtype group." (PMID 38791477, 2024). "Abnormal expression levels of specific molecules like LPL, FATP2, and CPT1A have been linked to tumor progression and poor prognosis." (PMID 37795451, 2023). "LPL is an important enzyme that is secreted by extracellular lipolysis and can potentially be supplied by tumor cells or adjacent adipose tissue cells into the tumor microenvironment." (PMID 37298233, 2023). "Meanwhile, lipid staining showed a mass of lipids in obese N + tumor samples, and IHC analysis indicated an increase in LPL and CD36 expression in N + cases, implying a crucial role for exogenous lipid supply in LNM." (PMID 36397145, 2022). "Reduced levels of fatty acid synthase (FAS) and lipoprotein lipase (LPL were demonstrated in adipose tissue from cachectic cancer patients and animal tumor models." (PMID 35646636, 2022). "LPL enhances the uptake of fatty acids by tumor cells, and suppression of LPL reinforces the effect of FAS blockage on cell proliferation." (PMID 34629057, 2021). "By quantitatively analyzing and comparing the number and volume of tumor masses formed at 20 weeks, LPL, FABP4 or CPT1 inhibitors significantly reduced liver carcinogenesis in STAM mice, especially in the Orlistat group and BMS309403 group." (PMID 34803493, 2021). "Taken together, all these data suggest that, as the transcriptional target of ZHX2, LPL not only mediates lipids uptake of HCC cell lines but also promotes HCC tumor growth." (PMID 31740790, 2020). "Due to its catalytic activity, LPL is involved in metabolic pathways exploited by various solid and hematologic malignancies to provide an extra energy source to the tumor cell." (PMID 29206143, 2017). "LPL has been detected in a number of tumour types and has been shown to be critical in enabling cancer cells to acquire NEFAs from culture medium." (PMID 28866808, 2017). "It is possible that tumor-derived factors increase DC production of lipoprotein lipase, leading to increased triglyceride hydrolysis and availability of lipids for subsequent uptake by DCs." (PMID 25886502, 2015). "The location of tumor LPL is somewhat controversial as a recent study observed that increased LPL expression was in a subgroup of macrophages and not in cancer cells." (PMID 25866768, 2015). "The target gene ANGPTL4 is of particular interest in the context of the present study, since it not only figures in lipid metabolism as a regulator of lipoprotein lipase, but also plays an apparently essential role in tumor progression." (PMID 25968567, 2015).
tumor (continued). "In the study, we observed that tumour ROIs in radical prostatectomy specimens bore chromosomal abnormalities, including MYC amplification/gain, LPL and PTEN loss, TMPRSS2 rearrangement, as well as general aneuploidy." (PMID 24568597, 2014). "At early stages, plasma FFA decreased and LPL activity increased; however, at advanced stages of tumor, LPL activity decreased." (PMID 25415607, 2014). "The finding that elevated PEMT expression in NSCLC tissue predicts shorter patient survival independently of increased FASN or LPL activities further strengthens the evidence that lipid mobilization is required to sustain tumor growth." (PMID 24932311, 2014). "Sequenzial changes in the activities of LPL and lipogenic enzymes have been demonstrated in patients with tumor, as well as in animal model of cancer." (PMID 23110339, 2012). "At the advanced stage of cancer, the activity of lipoprotein lipase in vivo decreases, and in consequence, the level of oxLDL declines, promoting an uncontrolled proliferation of tumor cell." (PMID 21711568, 2011). "Expression of the LPL gene was down-regulated in tumor tissue compared to adjacent normal tissue in an identical fashion in both FF as well as FFPE samples." (PMID 21059268, 2010). "Also, lipolysis promotes tumor growth, and the association between lipolysis and cancer development has been confirmed by the increase in lipoprotein lipase (LPL) found in several studies, which also allows us to assess the prognosis of tumor therapy." (PMID 40696413, 2025). "These biological mechanisms are pivotal in influencing tumor invasiveness and metastatic potential, further indicating that LPL could be a significant contributor to the progression of malignant phenotypes in LUAD." (PMID 40427755, 2025). "In contrast, TMB primarily reflects the quantity of tumor-specific neoantigens derived from somatic mutations and is less related to metabolic state, thereby exhibiting a negative correlation with LPL." (PMID 40427755, 2025). "Notably, the clusters centered around ‘tumor microenvironment,’ ‘lipids,’ and ‘lipoprotein lipase’ emerged as focal points of research interest." (PMID 40231255, 2025). "This bidirectional correlation implies that LPL may have heterogeneous molecular functions in different tumor types or play different regulatory roles under different genetic mutation backgrounds." (PMID 40427755, 2025). "Tumor cells additionally obtain fatty acids (FAs) by initiating lipolysis, a process involving the breakdown of lipid droplets facilitated by lipoprotein lipase (LPL), resulting in the liberation of free FAs." (PMID 39969135, 2025). "LPL’s expression is not directly associated with the differentiation status of tumor cells, but is more influenced by the metabolic activity of immune and stromal cells within the tumor microenvironment." (PMID 40427755, 2025). "Reanalysis leveraging the TIMER2.0 database demonstrated substantial variations in LPL gene expression between tumor tissues and their corresponding normal counterparts across multiple tumor types, with significantly reduced LPL expression levels identified specifically in LUAD tissues." (PMID 40427755, 2025). "The results suggest that LPL could play an intricate role in regulating immune interactions within the tumor microenvironment." (PMID 40427755, 2025). "This suggests that LPL may influence tumor immune evasion and local immune regulation by modulating immune activities within the tumor microenvironment." (PMID 40427755, 2025). "This may be because patient survival in LUAD is governed by a multitude of factors—such as overall physiological status, adjuvant treatments, and tumor progression—of which LPL represents only one regulatory element." (PMID 40427755, 2025). "This inhibitory impact may be related to LPL inhibition, which prevents tumor cells from uptaking exogenous fatty acids." (PMID 38339301, 2024).
tumor (continued). "Furthermore, triptolide treatment’s effects on tumor growth inhibition decreased when LPL was knocked down." (PMID 38339301, 2024). "In addition, the transplanted tumor’s growth was slowed down by reduced expression of LPL, which also strengthened tripterygium’s ability to stop the tumor’s growth." (PMID 38339301, 2024). "This suggested that TP might prevent tumor cells from taking exogenous fatty acids by inhibiting LPL." (PMID 38339301, 2024). "LPL knockdown was employed to test the anti-tumor activity of triptolide." (PMID 38339301, 2024). "Furthermore, tripterygium’s growth-inhibitory effect on xenograft tumors was amplified by decreased LPL expression, which further inhibited xenograft tumor growth." (PMID 38339301, 2024). "Reducing LPL activity in the tumor microenvironment appears to be an attractive concept." (PMID 36652113, 2023). "Therefore, the LPL/FABP4/CPT1 axis would generate a tumor microenvironment providing fatty acids for building blocks and energy production (i.e., fatty acid oxidization), which is essential for the proliferation of tumor-initiating cells." (PMID 35052876, 2022). "In this study, the results of tumor spheroid culture and colony formation in vitro showed that small-molecule inhibitors of the LPL/FABP4/CPT1 axis, including Orlistat, BMS309403 and Etomoxir, could inhibit the activity of LCSCs." (PMID 34803493, 2021). "We speculated that this phenomenon may be related to the increased secretion of LPL into the peripheral blood by tumor cells in HCC patients." (PMID 34834495, 2021). "The activation of fatty acid metabolism regulated by the LPL/FABP4/CPT1 axis may provide a tumor microenvironment conducive to the production of LCSCs, although the detailed mechanism remains to be further explored." (PMID 34803493, 2021). "The reason for this phenomenon may be related to the increased secretion of LPL into the peripheral blood by tumor cells in HCC patients." (PMID 34834495, 2021). "Furthermore, immunohistochemical staining also revealed that the number of high-LPL specimens in the tumour group was more than that in the para-tumour group." (PMID 34976793, 2021). "In addition to the de novo synthesis of fatty acids, dietary fatty acids in the blood are decomposed into triglycerides by lipoprotein lipase (LPL) and transported into tumor cells by CD36 (a fatty acid transferase)." (PMID 34566954, 2021). "Notably, LPL overexpression induced by AAV-LPL not only increased the number of tumor nodes but also reversed the inhibitory effect of ZHX2 on tumor formation in STZ–HFD mice." (PMID 31740790, 2020). "Furthermore, ZHX2 overexpression suppressed the growth of xenograft tumors, while ectopic expression of LPL enhanced tumor growth, and clearly reversed the ZHX2-inhibited xenograft tumor growth." (PMID 31740790, 2020). "The human LPL gene has been mapped to chromosome 8p22 and previous studies on loss of heterozygosity (LOH) in colorectal tumors suggested that a putative tumor suppressor gene may lie within the short arm of chromosome 8, that is, 8p22-p21.3." (PMID 22028972, 2012). "Interestingly, tumor suppressive effects of LPL inducers, such as PPAR ligands, NO-1886, and indomethacin, have been demonstrated in animal models." (PMID 22028972, 2012). "Angiopoietin-like 4 (ANGPTL4, NM_016109), which increases triglycerides by potent inhibition of lipoprotein lipase, was increased in ccRCC tumor tissue by 23-fold and may play a major role in lipid accumulation." (PMID 20502531, 2010). "Furthermore, our comprehensive analysis indicates that the downregulation of tumor-specific LPL in LUAD may be attributed to transcriptional dysregulation." (PMID 40427755, 2025).
tumor (continued). "Therefore, preventing LPL activity may reduce proliferation of tumor cells by limiting the energy source." (PMID 38339301, 2024). "Additionally, we discovered that sh-LPL prevented HCC xenograft tumor growth." (PMID 38339301, 2024). "Therefore, it is suggested that the semi-quantitative measurements of whole-body tumor burden in 68Ga-pentixafor PET/CT might serve as a good biomarker for tracking disease burden in a particular patient with WM/LPL and for assessing treatment response." (PMID 34714390, 2021). "In vitro experiments also confirmed that the inhibition of these signaling molecules could effectively reduce the tumor spheroid formation, indicating that the activation of the LPL/FABP4/CPT1 axis in the NASH stage may be beneficial to the viability of TICs in liver tissue." (PMID 34803493, 2021). "In addition to FA synthesis, the rapidly growing tumor cells can employ lipoprotein lipase (LPL), catalyzing hydrolysis of lipoprotein triacylglycerides (TAG), and fatty acid transporter CD36, in order to acquire fatty acids from blood and, thus, further fuel their growth." (PMID 34206240, 2021). "Furthermore, inhibition of the LPL/FABP4/CPT1 axis could effectively delay the tumor growth in STAM mice." (PMID 34803493, 2021). "Dysregulated fatty acid metabolism, including enhanced lipoprotein lipase (LPL) activity and lipid droplet accumulation, provides a continuous supply of fatty acids to TAMs, supporting their tumor-promoting activities." (PMID 40177538, 2025). "Bioinformatics studies and cell function experiments suggest the multifaceted roles of LPL in LUAD, including tumor occurrence, immune regulation, metabolic regulation, and targeted drug therapy." (PMID 40427755, 2025). "At the multi-cancer type level, the correlation between LPL expression levels and TMB and MSI reveals its potential role in tumor genomic instability." (PMID 40427755, 2025). "The patient cohort consisted of nine patients diagnosed with five different states on the PC neoplasia continuum, from MGUS to RRMM, with an additional patient with LPL and two age-matched NDs as controls." (PMID 36362214, 2022). "In colorectal cancer patients, decreased activity of LPL and FAS was shown in the adipose tissue adjacent to the tumor." (PMID 35646636, 2022). "While the comparison of expression data between tumor and normal samples showed that 8 out of 36 ARGs were significantly differentially expressed, including CCND2, CXCL6, KCNJ8, LPL, SERPINA5, SLCO2A1, VTN, and APOH." (PMID 35836112, 2022). "Here, our findings indicated the upregulation of LPL in PTC and the direct correlation of LPL expression with tumour size and lymph node metastasis." (PMID 34976793, 2021). "LPL, as a unique downstream target of CD44 signal transduction, can activate endothelial cell-mediated angiogenesis during tumor growth." (PMID 34834495, 2021). "Considering that the TG content was considerably low and proteomic analysis was semi quantitative, WB and IHC were performed to confirm LPL expression in the PTC and para-tumor specimens." (PMID 34976793, 2021). "Lipogenic enzymes, such as lipoprotein lipase (LPL) and fatty acid synthase (FAS), are significantly reduced in the adipose tissue adjacent to the tumor, validating the tumor-supporting role of WAT in CAC." (PMID 32117967, 2020). "ZHX2 overexpression decreased Ki67+ cells, while ectopic LPL elevated Ki67+ tumor cells and restored Ki67 expression in ZHX2 tumor cells." (PMID 31740790, 2020). "Chromosomal abnormalities of MYC, LPL and PTEN, and aneusomy (as measured by copy number changes of the chromosome-specific CEP probes) were observed in tumour ROIs of the radical prostatectomy specimens." (PMID 24568597, 2014).